NNMT (nicotinamide N-methyltransferase)
Diseases named in the same sentence as NNMT in open-access papers (continued):
Sharing a sentence is not in itself a finding about the gene and the disease.
Obesity (continued). "Likewise, treatment with the selective NNMT inhibitors 5-amino-1-methylquinoline or 6-methoxynicotinamide resulted in reduced body weight, higher insulin sensitivity, and improved glucose tolerance in mice with diet-induced obesity." (PMID 33668468, 2021). "NNMT protein levels are upregulated in the liver and adipose tissue of mouse models of insulin resistance and obesity, and NNMT knockdown has a protective effect against the metabolic consequences of HFD, suggesting that NNMT may have a critical role in NAFLD pathogenesis." (PMID 31510030, 2019). "Theoretically, it is not surprising that NNMT gene is significantly associated with obesity." (PMID 29075643, 2017). "Elevated NNMT gene expression is notably observed in the liver and white adipose tissue (WAT) of individuals with diabetic mice, obesity, and rats afflicted with MetS." (PMID 38919254, 2024). "Accumulating evidence shows that NNMT regulates histone methylation, polyamine flux, and NAD+-dependent SIRT1 signaling, making it a novel target for treating obesity and type 2 diabetes." (PMID 37371959, 2023). "As a proof of concept, NNMT knock-down in the WAT and liver protected against diet-induced obesity, where it modifies the intracellular content of SAM and NAD+, two crucial mediators of cellular energy metabolism." (PMID 37217546, 2023). "Therefore, we speculated that NNMT might participate in obesity regulation through autophagy." (PMID 35603729, 2022). "Collectively, NNMT’s master regulatory involvement in key metabolic processes in the metabolically active tissues (adipose, liver, and muscle) suggests that NNMT may represent an attractive, druggable target serving as a niche access point to treat obesity and related chronic metabolic diseases." (PMID 33707534, 2021). "Knockdown of NNMT in WAT and liver in mice protects against diet-induced obesity by increasing cellular energy expenditure." (PMID 29445118, 2018). "Nicotinamide-N-methyltransferase (NNMT) was recently shown to be upregulated in mouse models of insulin resistance and obesity." (PMID 25596852, 2015). "NNMT expression both in white adipose tissue (WAT) and in liver was recently found to be upregulated in mouse models of obesity and diabetes." (PMID 25596852, 2015). "Furthermore, the use of inhibitors in treating metabolic disorders such as obesity and diabetes has been suggested via using small molecules such as JBSNF-000028 to inhibit NNMT activity, thereby improving glucose tolerance after treatment." (PMID 38397953, 2024). "Interestingly, NNMT, the enzyme that catalyzes the reaction of methylation of NAM for its excretion, is up-regulated in the WAT in obesity and T2D." (PMID 37761000, 2023). "With NNMT as a linker between DNL and ccRCC along with NAD metabolism as a well-established factor in obesity, NNMT and NAD may be additional molecular clues to the intriguing relationship between obesity and ccRCC." (PMID 36750850, 2023). "Previous research has indicated that overexpression of NNMT can have negative impacts in diet-induced obesity." (PMID 37953778, 2023). "These congruent results conclusively demonstrate that NNMT is a key component of the GC-CEBP axis during the early stages of adipogenesis and could be a potential therapeutic target for both early-onset obesity and glucocorticoid-induced obesity." (PMID 37217546, 2023). "Indeed, NNMT knockout in mice—resulting in higher nicotinamide and reduced NMND and 2PY—is protective of diet-induced obesity." (PMID 33262239, 2020). "NNMT has been proposed as a pharmacological target for treating obesity and type 2 diabetes based on higher NNMT expression and plasma MNA levels in individuals with obesity or T2D and animal studies using antisense-oligonucleotide mediated knockdown of NNMT3,4,6." (PMID 29483571, 2018).
Obesity (continued). "Additionally, trials of oligonucleotide therapeutics and some small-molecule NNMT inhibitors in vitro and in preclinical animal models have validated NNMT as a promising therapeutic target to prevent or treat obesity and related T2D, but currently, clinical trials have not yet been reported." (PMID 34368359, 2021).
breast carcinoma (34 papers, 2014 to 2026). "To explore the underlying biological process regulated by NNMT in breast cancer cells, we compared the proteome between control shRNA and NNMT‐shRNA transfected MDA‐MB‐231 cells by protein mass spectrometry analysis." (PMID 38126621, 2024). "For cancer, NNMT was primarily implicated in poor prognosis or metastasis in various tumors such as pancreatic, gastric, ovarian, breast cancer, and glioblastoma." (PMID 36750850, 2023). "Consistently, NNMT silencing is linked with apoptosis of breast cancer cells, as well as the decreased tumorigenicity of non-small cell lung cancer cells, oral carcinoma cells, and glioblastoma cells." (PMID 33193702, 2020). "According to our study, NNMT has the potential to become a biomarker for diagnostic and chemotherapeutic efficacy predication in breast cancer." (PMID 31101119, 2019). "Given the findings of this study and the previously reported metastasis‐promoting role of NNMT in breast cancer, it is crucial and significant to develop diagnostic kits for the detection of NNMT in breast cancer and to explore NNMT inhibitors for therapeutic purposes in breast cancer." (PMID 38126621, 2024). "Furthermore, NNMT expression was associated with breast cancer resistance to adriamycin and paclitaxel, colorectal cancer resistance to 5-fluorouracil (5-FU), and melanoma resistance to dacarbazine." (PMID 38396769, 2024). "In this study, the upregulation of NNMT was observed in CTCs from breast cancer patients and mouse CTCs models." (PMID 41816955, 2026). "For example, NNMT expression reduced apoptosis induced by adriamycin or paclitaxel in breast cancer cells." (PMID 40853419, 2025). "To verify the contribution of NNMT to breast cancer progression, we examined NNMT expression in eight breast cancer cell lines (SKBR3, MCF7, MDA‐MB‐231, BT‐549, HCC1937, Bcap37, T47D, and MDA‐MB‐468) by western‐blot." (PMID 38126621, 2024). "In this research, we found that NNMT expression in breast cancer tissue showed positive correlation with tumor size, histological grade, and tumor cell proliferation (Ki‐67 index), and high level of NNMT predicts poor survival." (PMID 38126621, 2024). "Previous studies have reported elevated NNMT expression in colorectal and breast cancers, promoting tumor growth, and metastasis, respectively." (PMID 38809277, 2024). "Collectively, we verified that high expression of NNMT in breast cancer cells contributes to cell‐cycle progression, cell proliferation, and serves as a poor prognostic factor in breast cancer." (PMID 38126621, 2024). "According to these results, we clarified that NNMT/1‐MNA is a positive upstream regulator of the neddylation pathway in breast cancer." (PMID 38126621, 2024). "Collectively, our study identified UBC12 as a intracellular target protein of 1‐MNA and demonstrated that NNMT/1‐MNA pathway promote breast cancer progression through engaging neddylation‐mediated degradation of p27 proteins." (PMID 38126621, 2024). "To verify if p27 protein degradation is mediated by NNMT in breast cancer, we treated breast cancer cells with cycloheximide (CHX) to block new protein synthesis." (PMID 38126621, 2024). "Specifically, higher protein expression levels of NNMT were observed in most tumors, including breast cancer, colorectal cancer, clear cell RCC, lung cancer, and several others." (PMID 38809277, 2024). "Here, 1‐methyl‐nicotinamide (1‐MNA), metabolite of nicotinamide N‐methyltransferase(NNMT) is identified, as a novel driver of cell‐cycle progression in breast cancer." (PMID 38126621, 2024). "Upregulation of NNMT maintains the cancer-associated fibroblast phenotype, activates the PRDM5/COL1A1 axis, and promotes tumor metastasis in gastric cancer and breast cancer (BC)." (PMID 39399490, 2024).
breast carcinoma (continued). "An example of this is the enzyme Nicotinamide N-methyltransferase (NNMT) which promotes epigenetic remodeling in breast cancer and affects all other NAD+ dependent enzymes such as poly-ADP ribose polymerases (PARPs) and sirtuins." (PMID 38137912, 2023). "Similar results also indicated that NNMT expression was significantly higher and correlated with poor survival in breast cancer, colorectal cancer, gastric cancer, and OV." (PMID 36817086, 2023). "Currently, the analysis of proteomic data has revealed that NNMT is expressed in various cancer types, including breast cancer, bladder cancer, gastric cancer, liver cancer, colorectal cancer, ovarian cancer, oral squamous cell carcinoma, and skin cancer." (PMID 35884600, 2022). "NNMT expression was found to be associated with TMB in 14 types of tumors, including breast cancer, colorectal cancer, lung cancer, glioma, and kidney cancer." (PMID 36386816, 2022). "These together suggested that 4T1 breast cancers increase MNAM not only via NNMT upregulation but also via downregulation of Aox genes (i.e., suppression of MNAM degradation)." (PMID 35705545, 2022). "Based on these datasets, NNMT appeared to be involved in dysregulation of the urea cycle and in enhanced uracil biogenesis in the 4T1 breast cancer-bearing condition." (PMID 35705545, 2022). "Nicotinamide N-methyltransferase inhibits the autophagy induced by oxidative stress in breast cancer cells." (PMID 35603729, 2022). "In breast cancer patients, NNMT expression was reported to correlate with shorter survival and resistance to chemotherapy." (PMID 34073600, 2021). "Given that NNMT is inversely correlated with H2O2-induced autophagy in breast cancer cells, we further explored the potential mechanisms by which NNMT regulates autophagy." (PMID 32489327, 2020). "We reported in our previous papers that NNMT overexpression inhibits the apoptosis and enhances the chemotherapy resistance of breast cancer cells." (PMID 32489327, 2020). "In this study, we examined the expression of NNMT and LC3B II, a marker of autophagy in breast cancer cell line models with NNMT overexpression or knockdown, and then determined correlation between them." (PMID 32489327, 2020). "Recently, we reported that NNMT is overexpressed in breast cancer patients’ tumours and increases the resistance to chemotherapy via its product 1MNA." (PMID 32489327, 2020). "Our previous and current studies have shown that NNMT plays a role both in regulating apoptosis and autophagy in breast cancer." (PMID 32489327, 2020). "Considering that the NNMT gene was predicted to be an autophagy regulator by genome-wide analysis, we investigated the role of NNMT in the autophagy of breast cancer cells." (PMID 32489327, 2020). "Together, our results demonstrate that NNMT expression negatively regulates autophagy by inhibiting the activation of the AMPK-ULK1 pathway in breast cancer cells to offer survival advantages to cancer cells under oxidative stress." (PMID 32489327, 2020). "In summary, our study demonstrated for the first time that NNMT is overexpressed in breast carcinoma and that a high level of NNMT expression correlates with poor survival and an unfavorable therapy response in patients who received chemotherapy." (PMID 31101119, 2019). "At the beginning of this study, we found that NNMT was upregulated in breast carcinomas of patients who were undergoing mastectomy by immunohistochemistry on tissue microarray (p < 0.001)." (PMID 31101119, 2019). "Taken together, these results suggest that NNMT is a promising new therapeutic target for breast cancer treatment." (PMID 31101119, 2019). "NNMT expression in breast carcinoma was examined by immunohistochemistry, and then, its relationship with patient clinicopathological characteristics was analyzed." (PMID 31101119, 2019).
breast carcinoma (continued). "Taken together, these results indicated that the down-regulation of NNMT in breast cancer cells resulted in activation of the mitochondria-mediated apoptotic pathway." (PMID 24558488, 2014). "The silencing reciprocal effect of NNMT was confirmed by over-expressing NNMT in the MCF-7 and SK-BR-3 breast cancer cell lines which lack constitutive expression of NNMT." (PMID 24558488, 2014). "Efficient down-regulation of NNMT resulted in markedly reduced breast cancer cell growth both in Bcap-37 and MDA-MB-231 cell lines." (PMID 24558488, 2014). "The underlying molecular mechanisms of the apoptosis promoted by down-regulation of NNMT in breast cancer cells would further clear the role of NNMT in cancer cells." (PMID 24558488, 2014). "The dexamethasone-dependent overexpression of NNMT is likely relevant to tumor types other than glioblastoma, as suggested by a proteomic screen that identified “nicotinamide metabolism” as a process activated by GR in breast cancer cells." (PMID 41576167, 2026). "We hypothesize that p27, other than p21, is the downstream target of NNMT involved in promoting cell‐cycle progression in breast cancer cells." (PMID 38126621, 2024). "Therefore, we believe that the role of NNMT/1‐MNA in breast cancer is not limited to cell cycle regulation and tumor metastasis." (PMID 38126621, 2024). "These confirmed the role of NNMT in promoting breast cancer cell proliferation." (PMID 38126621, 2024). "Taken together, NNMT expression is elevated in breast cancer, and high level of NNMT may promote cancer progression by regulating cancer cell proliferation." (PMID 38126621, 2024). "High NNMT expression was shown to be an unfavorable postoperative prognosis in breast cancer, head and neck squamous cell carcinoma, renal cancer, non-small cell lung cancer, colorectal cancer, pancreatic cancer, liver cancer, gastric cancer, ovarian cancer and endometrial cancer." (PMID 36386816, 2022). "To deeper understand the biological roles of NNMT in 4T1 breast cancer-induced abnormalities in liver metabolism, we tried to identify metabolic pathways that were regulated by NNMT in the 4T1-bearing condition with the aid of integrating transcriptome and metabolome datasets." (PMID 35705545, 2022). "Overexpression of NNMT in breast cancer cell lines SK-BR-3 (ER−, HER2+) and MCF7 (ER+, HER2−), which constitutively do not express NNMT, significantly inhibited doxorubicin (adriamycin)- and paclitaxel-mediated apoptotic cell death and suppression of colony formation." (PMID 34073600, 2021). "In a previous study, we reported that NNMT expression increases its product 1MNA level in cancer cells, which decreases intracellular ROS levels to inhibit mitochondria-mediated apoptosis in breast cancer cells and to suppress 5-FU-induced apoptosis in colorectal cancer cells." (PMID 32489327, 2020). "However, the detailed mechanism by which NNMT regulates the balance between apoptosis and autophagy in breast cancer cells needs further study." (PMID 32489327, 2020). "Combined with our results, we hypothesized that NNMT and its product 1MNA negatively regulate autophagy by suppressing the increase in ROS induced by oxidative stress in breast cancer cells." (PMID 32489327, 2020). "In this study, we first found that NNMT is involved in autophagy regulation in breast cancer cells." (PMID 32489327, 2020). "In breast cancer, NNMT was found to be overexpressed in several cell lines." (PMID 31101119, 2019). "The NNMTh percentage of breast cancer samples was 53.9% (89/165), which was significantly higher than that of paracancerous tissues (13.3%) and breast hyperplasia (10.0%) (p < 0.001), which indicates that NNMT expression was upregulated in breast cancer." (PMID 31101119, 2019). "Interestingly, down-regulation of NNMT increased ROS production in human breast cancer cell lines was found." (PMID 24558488, 2014).
breast carcinoma (continued). "In the present study, we showed that NNMT was selectively expressed in some breast cancer cell lines, down-regulation of NNMT expression in Bcap-37 and MDA-MB-231 cell lines by NNMT shRNA significantly inhibited cell growth in vitro, decreased tumorigenicity in mice and induced apoptosis." (PMID 24558488, 2014). "In the present study, we investigated the expression of NNMT in human breast cancer cell lines and found that shRNA targeted against NNMT significantly decreased cell growth, inhibited tumorigenicity in mice and induced apoptosis via the mitochondria-mediated pathway." (PMID 24558488, 2014). "Although the definite mechanism of its role needs to be further studied, NNMT may become a promising candidate for breast cancer therapy." (PMID 24558488, 2014). "In the present study, we observed that the expression of Bax and Puma was up-regulated, while the expression of Bcl-2 and Bcl-xL was significantly down-regulated in NNMT shRNA infected breast cancer cells, which resulted in the increase of the ratio of Bax/Bcl-2." (PMID 24558488, 2014). "We confirmed high expression of NNMT in some of the breast cancer cell lines, however, the role of NNMT in breast cancer is largely unknown." (PMID 24558488, 2014). "NNMT upregulation in the SK-BR-3 breast cancer (BC) cell line, lacking endogenous NNMT expression, greatly reduced ROS-associated autophagy, while this effect was reversed following enzyme knockdown in MDA-MB-321 BC cells, originally displaying elevated NNMT levels." (PMID 41301471, 2025). "However, in breast cancer, the precise biological role of NNMT and its metabolite 1‐MNA in cell‐cycle progression, as well as the underlying mechanisms, remain largely unknown and undisclosed." (PMID 38126621, 2024). "Therefore, NNMT downregulation might be a therapeutic strategy for the combined treatment of breast cancer." (PMID 32489327, 2020). "Therefore, we investigated the role of NNMT in breast cancer chemotherapy, which might be beneficial for improving chemotherapeutic efficacy in breast cancer." (PMID 31101119, 2019). "Moreover, targeting NNMT or downstream SIRT1 may represent a new therapeutic approach to improve the efficacy of breast cancer chemotherapy." (PMID 31101119, 2019). "Our study revealed that the upregulation of NNMT is induced by FAK-STAT3 axis, which contributes to CTCs anoikis resistance in breast cancer by activating FAO." (PMID 41816955, 2026). "However, whether NNMT participates in breast cancer CTCs anoikis remains unexplored." (PMID 41816955, 2026). "This study investigated the expression profile and prognostic significance of nicotinamide N-methyltransferase (NNMT) in pan-cancer stroma, with focused validation in lung adenocarcinoma (LUAD) and breast carcinoma (BC)." (PMID 41913584, 2026). "Supporting this, nicotinamide N-methyltransferase (NNMT) decreases phosphatase PP2A methylation, which induces EMT via MEK activation in breast cancer cells and promotes migration while increasing ADAMTS6 expression in renal cancer cells." (PMID 41465277, 2025). "In this study, it is demonstrated that the NNMT‐specific metabolite, 1‐methyl‐nicotinamide (1‐MNA), promotes breast cancer cell‐cycle progression by enhancing CRL1‐mediated degradation of p27 proteins." (PMID 38126621, 2024). "In vitro and in vivo experiments of NNMT silencing in Bcap-37 and MDA-MB-231 human breast cancer cell lines showing high enzyme levels led to apoptosis induction and significantly reduced cell growth and tumorigenicity." (PMID 38504052, 2024). "NNMT was also reported to regulate the expression/activity of SIRT1 in prostate and breast cancer cells by supporting SIRT1 stabilization." (PMID 38396769, 2024).